CACNG8 (calcium voltage-gated channel auxiliary subunit gamma 8)
Description:
Regulates the activity of L-type calcium channels that contain CACNA1C as pore-forming subunit (By similarity). Regulates the trafficking and gating properties of AMPA-selective glutamate receptors (AMPARs). Promotes their targeting to the cell membrane and synapses and modulates their gating properties by slowing their rates of activation, deactivation and desensitization and by mediating their resensitization. Does not show subunit-specific AMPA receptor regulation and regulates all AMPAR subunits.
Tractability: Small molecule: an approved drug acts on it; a high-quality ligand is known; it belongs to a druggable protein family. Antibody: its Gene Ontology location is reachable by antibodies, with high confidence; UniProt places it where antibodies can reach, with medium confidence; UniProt predicts a signal peptide or a membrane-spanning region. PROTAC: its protein half-life has been measured; a small molecule that binds it is known.
Gene: Protein-coding gene on chromosome 19 (53,962,937 to 53,990,215, forward strand). Ensembl gene ENSG00000142408.
Subcellular location: Cell membrane; Postsynaptic density membrane
Pathways (Reactome):
Muscle contraction: Phase 0 - rapid depolarisation; Phase 2 - plateau phase
Developmental Biology: LGI-ADAM interactions
Neuronal System: Trafficking of AMPA receptors
Gene Ontology:
Molecular function: protein binding; calcium channel regulator activity; channel regulator activity; voltage-gated calcium channel activity; ionotropic glutamate receptor binding; protein phosphatase 2B binding
Biological process: regulation of AMPA receptor activity; calcium ion transport; positive regulation of synaptic transmission, glutamatergic; postsynaptic neurotransmitter receptor diffusion trapping; transmission of nerve impulse; calcium ion transmembrane transport
Cellular component: AMPA glutamate receptor complex; endocytic vesicle membrane; L-type voltage-gated calcium channel complex; plasma membrane; postsynaptic density; postsynaptic density membrane; voltage-gated calcium channel complex; dendrite membrane; glutamatergic synapse; membrane; postsynaptic membrane
Genetic constraint (gnomAD): Loss-of-function variants: 4 observed, 22.37 expected, observed/expected ratio (o/e) 0.18, 90% interval 0.087 to 0.41. The synonymous counts are far from expectation, so gnomAD's model fits this gene poorly and the ratio says little. Missense variants: 441 observed, 501.77 expected, observed/expected ratio (o/e) 0.88, 90% interval 0.81 to 0.95. Synonymous variants: 291 observed, 239.53 expected, observed/expected ratio (o/e) 1.21, 90% interval 1.1 to 1.34.
Homologues: Orthologues: chimpanzee CACNG8 (99% identical), pig CACNG8 (96% identical), mouse Cacng8 (94% identical), rat Cacng8 (94% identical), macaque CACNG8 (90% identical), dog CACNG8 (87% identical), tropical clawed frog cacng8 (65% identical), zebrafish cacng8b (57% identical), zebrafish cacng8a (56% identical), Caenorhabditis elegans stg-2 (16% identical). Paralogues in human: CACNG4 (47% identical), CACNG2 (45% identical), CACNG3 (44% identical), CACNG5 (20% identical), CACNG7 (20% identical).
Diseases named in the same sentence as CACNG8 in open-access papers:
CACNG8 is named in the same sentence as 16 diseases in open-access papers, as found by Europe PMC text mining. Sharing a sentence is not in itself a finding about the gene and the disease. The quoted sentences say what the papers report.
schizophrenia (2 papers, 2023). A major psychotic disorder characterized by abnormalities in the perception or expression of reality. "Some of the candidate genes are also known to play a role in neuronal diseases like Alzheimer’s disease (EIF4B), schizophrenia (CACNG8) or Parkinson’s disease (TNR)." (PMID 36624125, 2023).
epilepsy (1 paper, 2025). A brain disorder characterized by episodes of abnormally increased neuronal discharge resulting in transient episodes of sensory or motor neurological dysfunction, or psychic dysfunction. "In addition, no pathogenic variants exclusively associated with epilepsy or seizures have been identified for CACNG7 and CACNG8." (PMID 40313715, 2025).
preeclampsia (1 paper, 2021). Preeclampsia is a hypertensive disorder of pregnancy that is characterized by new-onset hypertension with proteinuria presenting after 20 weeks of gestation, and depending on mild or severe forms may initially present with severe headache, visual disturbances, and hyperreflexia. "CACNG8, which was confirmed to encode calcium channels implicated in cardiac contraction, was identified as a calcium flux-related gene that depresses ventricular function and might thus account for long-term CVD in preeclampsia patients." (PMID 33959635, 2021).
Retinal dystrophy (1 paper, 2022). Retinal dystrophy is an abnormality of the retina associated with a hereditary process. "Many gene mutations in ocular ion channels were reported (e.g., CACAN1A, CACNG8, CNGB3) to contribute to retinal dystrophy." (PMID 36431052, 2022).
Stroke (1 paper, 2025). Sudden impairment of blood flow to a part of the brain due to occlusion or rupture of an artery to the brain. "In contrast, no stroke-related literature was found for CACNG8, a protein primarily recognized as an auxiliary subunit of AMPA-type glutamate receptors." (PMID 41342963, 2025).
psychiatric disorder (3 papers, 2020 to 2023). A disorder characterized by behavioral and/or psychological abnormalities, often accompanied by physical symptoms. "TARP γ-8 (also known as CACNG8) preferentially expresses in the hippocampus, cortex and subcortical regions that are critical for emotion generation indicating its association with psychiatric disorders." (PMID 34099816, 2021).
neurological disorders (1 paper, 2025). "The up-regulated CACNG8, which was positively regulated by the uniquely expressed circPRDM2 in a recent transcriptomic study where they found negative influences of cannabinol to ion channels and synaptic transmission, eventually mediating neurological disorders." (PMID 41327336, 2025).
CACNG8 also shares sentences with these, for which no sentence is quoted: dilated cardiomyopathy (2 papers); Alzheimer disease (1); arrhythmogenic right ventricular cardiomyopathy (1); carcinoma (1); cardiomyopathy (1); hypertrophic cardiomyopathy (1); neurodegenerative disease (1); neurodevelopmental disorder (1); Parkinson disease (1).